NRXN3 (neurexin 3)
Description:
Neuronal cell surface protein that may be involved in cell recognition and cell adhesion. May mediate intracellular signaling (By similarity). Functions as part of a trans-synaptic complex by binding to cerebellins and postsynaptic GRID1. This interaction helps regulate the activity of NMDA and AMPA receptors at hippocampal synapses without affecting synapse formation. NRXN3B-CBLN2-GRID1 complex transduce presynaptic signals into postsynaptic AMPAR response (By similarity). Neuronal cell surface protein that may be involved in cell recognition and cell adhesion. May mediate intracellular signaling (By similarity).
Synonyms: C14orf60; KIAA0743
Tractability: Antibody: its Gene Ontology location is reachable by antibodies, with high confidence; UniProt places it where antibodies can reach, with medium confidence; UniProt predicts a signal peptide or a membrane-spanning region. PROTAC: its protein half-life has been measured.
Gene: Protein-coding gene on chromosome 14 (78,170,373 to 79,868,291, forward strand). Ensembl gene ENSG00000021645.
Subcellular location: Presynaptic cell membrane
Pathways (Reactome):
Neuronal System: Neurexins and neuroligins
Gene Ontology:
Molecular function: protein binding; cell adhesion molecule binding; neuroligin family protein binding; signaling receptor activity; transmembrane signaling receptor activity
Biological process: adult behavior; learning; social behavior; vocalization behavior; axon guidance; gephyrin clustering involved in postsynaptic density assembly; nervous system development; neuron cell-cell adhesion; signal transduction
Cellular component: plasma membrane; presynaptic active zone membrane; presynaptic membrane; trans-synaptic protein complex
Genetic constraint (gnomAD): Loss-of-function variants: 29 observed, 124.07 expected, observed/expected ratio (o/e) 0.23, 90% interval 0.17 to 0.32. The upper end of that interval is the gene's LOEUF score, 0.32, which puts it in group 1 of 6, group 1 being the genes least tolerant of losing a copy. Missense variants: 1,535 observed, 2,054 expected, observed/expected ratio (o/e) 0.75, 90% interval 0.72 to 0.78. Synonymous variants: 790 observed, 792.47 expected, observed/expected ratio (o/e) 1, 90% interval 0.94 to 1.06.
Homologues: Orthologues: macaque NRXN3 (99% identical), chimpanzee NRXN3 (99% identical), guinea pig NRXN3 (98% identical), mouse Nrxn3 (98% identical), rabbit NRXN3 (98% identical), rat Nrxn3 (97% identical), tropical clawed frog nrxn3 (85% identical), dog NRXN3 (85% identical), zebrafish nrxn3a (57% identical), pig NRXN3 (54% identical). Paralogues in human: NRXN1 (66% identical), NRXN2 (66% identical), CNTNAP5 (20% identical), CNTNAP2 (20% identical), CNTNAP4 (19% identical), CNTNAP3 (19% identical), CNTNAP3B (19% identical), CNTNAP1 (18% identical), CUBN (10% identical), F5 (10% identical), F8 (10% identical), HEPH (10% identical), and 23 more.
Diseases named in the same sentence as NRXN3 in open-access papers:
NRXN3 is named in the same sentence as 82 diseases in open-access papers, as found by Europe PMC text mining. Sharing a sentence is not in itself a finding about the gene and the disease. The quoted sentences say what the papers report.
Obesity (23 papers, 2009 to 2025). Accumulation of substantial excess body fat. "GWA studies have identified variants in NRXN3 associated with increased waist circumference, BMI, and obesity." (PMID 41082226, 2025). "Neurexin-3 (Nrxn3) has been genetically associated with obesity, but the underlying neural mechanisms remain poorly understood." (PMID 39090731, 2024). "A QTL for glucose content was identified with a marker on SSC7 (ALGA0110857) close NRXN3 gene (position 101,132,780–102,779,809) which has been associated with human obesity and energy balance." (PMID 31065004, 2019). "Genetic variants in NRXN3 have been associated with increased waist circumference and obesity, which are important risk factors for and features of type 2 diabetes and central obesity is a risk factor for DR." (PMID 29739359, 2018). "The NRXN3 gene has been found to be associated with general obesity." (PMID 38998055, 2024). "NRXN3 gene has been associated with waist circumference as an obesity trait." (PMID 32982666, 2020). "The NRXN3 gene has been previously associated with central nervous system disorders and obesity, so its role in obesity could be a result of alterations to the nervous system." (PMID 31341224, 2019). "NRXN3 is expressed in the brain, as many of the other recently discovered obesity loci, and variants in NRXN3 may provide changes of the brain function and behavior." (PMID 21674055, 2011). "Our findings establish that common variants in NRXN3 are associated with WC, BMI, and obesity." (PMID 19557197, 2009). "The NRXN3 gene has been previously implicated in addiction and reward behavior, lending further evidence that common forms of obesity may be a central nervous system-mediated disorder." (PMID 19557197, 2009). "Moreover, NRXN3 is a gene associated with obesity, and we speculated that NRXN3 participates in lipid metabolism." (PMID 38575966, 2024). "We next examined obesity-related quantitative traits (such as total body weight, waist circumference and waist to hip ratio), and detected genome-wide significant signals between waist to hip ratio and NRXN3 (rs11624704, P = 2.67×10−9), previously associated with body weight and fat distribution." (PMID 21552555, 2011). "Other genes containing SNP variants associated with obesity and related traits in children and adolescents are the Fas apoptotic inhibitory molecule 2 (FAIM2) and neurexin 3 (NRXN3)." (PMID 41082226, 2025). "Selective ablation of Nrxn3 in the PVN resulted in marked obesity and glucose intolerance, despite normal appetite and locomotor activity." (PMID 39090731, 2024). "The genes reviewed here are FTO, NRXN3, NPC1, NEGR1, MTCH2, and GNPDA2, which were chosen for their association with obesity and their influence on NDgD or NDvD." (PMID 32982666, 2020). "NRXN3 has previously been reported to play an important role in mental disorders and behavior, and is a compelling biological candidate for obesity." (PMID 24265751, 2013). "Nineteen loci have been identified and five of them only are associated with BMI / obesity (FTO, MC4R,NRXN3, TFAP2B, MSRA)." (PMID 22043164, 2011). "However, there have been no direct reports on the role of neurexin-3 in regulating energy metabolism or obesity, and the neural circuits and mechanisms through which neurexin-3 influence energy balance remain largely undefined." (PMID 39090731, 2024). "Furthermore, Nrxn3 CKO mice exhibited hyperglycemia and glucose intolerance, which are hallmarks of obesity-associated metabolic dysfunction." (PMID 39090731, 2024). "This offers new understanding of how Nrxn3 dysfunction contributes to obesity, suggesting that targeting Nrxn3-dependent pathways in the PVN might lead to innovative treatments for obesity prevention and management." (PMID 39090731, 2024).
Obesity (continued). "Interestingly, some genes associated with obesity were also associated with AD by different genetic approaches: candidate gene approach FTO, by differentially expressed genes NRXN3, NPC1, NEGR1, or by GWAS approach: LEPR, BDNF, TNFα, and MTCH2." (PMID 32982666, 2020). "Interestingly, NRXN3 was significantly associated with waist-circumference in a large analysis by the CHARGE consortium, with BMI by the GIANT consortium and clinical measures of overweight and obesity." (PMID 26158673, 2015). "This study aims to bridge this knowledge gap by investigating the function of neurexin-3 in the PVN and its potential involvement in the neural control of energy balance and obesity development." (PMID 39090731, 2024). "Given the sex differences in obesity development and consequences, future studies should examine whether PVN Nrxn3 plays a similar role in regulating energy balance in females, since our current study focused on male mice." (PMID 39090731, 2024). "However, analyses were made without adjusting for multiple testing, and further studies are needed to confirm the putative role of LYPLAL1, NRXN3, MSRA, and TFAP2B in the pathophysiology of obesity." (PMID 21674055, 2011). "However, analyses were made without adjusting for multiple testing, and further studies are needed to elucidate the involvement of LYPLAL1, NRXN3, MSRA, and TFAP2B in the pathophysiology of obesity." (PMID 21674055, 2011).
autism (18 papers, 2012 to 2023). Persistent deficits in social interaction and communication and interaction as well as a markedly restricted repertoire of activity and interest as well as repetitive patterns of behavior. "For instance, neurexin 3 has been linked to autism, whereas SV2A and VAMP are associated with schizophrenia." (PMID 34827371, 2021). "The results of family cosegregation studies indicate that NRXN3 affects autism and neurodevelopment/neuropsychiatric disorders." (PMID 35309141, 2022). "On the contrary to our expectations, dog cfa6.7 that also maps in GALNT17, aligns with three different human genes (NRXN3, SLC9A7 and 15 kb upstream SPRY3) that are already involved in autism, two of which are X-linked." (PMID 34680999, 2021). "In addition, abnormal expression of NRXN3 is related to autism, addiction, schizophrenia, Alzheimer's disease, and other diseases." (PMID 37786892, 2022). "Likewise, many neuronal genes with H3K27ac gain and increased expression under CHD2 deficient conditions are linked to the etiology of autism and other NDDs, including MYT1L, NRXN3, SLC12A5, and SNAP25 32–35." (PMID 36115870, 2022). "NRXN3 gene variants have been associated with autism, addiction, and schizophrenia, however, not fully investigated in Alzheimer’s disease." (PMID 30902061, 2019).
schizophrenia (17 papers, 2011 to 2024). A major psychotic disorder characterized by abnormalities in the perception or expression of reality. "Genomic alterations in NRXN genes (NRXN1, NRXN2, and NRXN3) are associated with neuropsychiatric disorders, including autism spectrum disorders and schizophrenia." (PMID 39518976, 2024). "NRXN3 single-nucleotide polymorphisms (SNP) have been implicated in schizophrenia and addiction, with one recorded SNP located close to SS5 altering the expression of Nrxn3(25b+)." (PMID 38358390, 2024). "NRXN3 mutations have been detected in autistic children from four families and a subsequent association study linked NRXN3 polymorphisms with schizophrenia." (PMID 28013231, 2017). "The association of NRXN3 polymorphisms with schizophrenia was also found in a large case-control study." (PMID 24265751, 2013). "Moreover, schizophrenia and facial deformities are potential new features of NRXN3 haploid deficiency." (PMID 35309141, 2022). "Besides fat distribution, NRXN3 has been associated with several other traits, including addictions and schizophrenia." (PMID 21552555, 2011). "These experiments showed a consistent and significant decrease in NRXN3 at the mRNA and protein level in cortical neurons from schizophrenia patients." (PMID 37507766, 2023). "Taken together, these results suggest a central role for the NRXN3 204 isoform in mediating synaptic differences in schizophrenia." (PMID 37507766, 2023). "After undertaking transcriptomic analyses of cortical neurons as well as knockdown and overexpression experiments, we identified the NRXN3 isoform 204 as a key NRXN3 isoform that mediates synaptic deficits in iPSC-derived cortical neurons in schizophrenia." (PMID 37507766, 2023). "We found that exposure to clozapine resulted in robust increases in dendritic spines and synapses in layer III cortical neurons and to increase levels of the NRXN3 204 isoform in the schizophrenia cortical neurons." (PMID 37507766, 2023). "Network analysis of differentially expressed genes led to identification of NRXN3 as a hub gene, and follow-up experiments showed specific reduction of the NRXN3 204 isoform in schizophrenia neurons." (PMID 37507766, 2023). "NRXN1 and NRXN3 expression was reduced in schizophrenia cortical neurons, and the NRXN3 reduction was the most robust and consistent between the different lines." (PMID 37507766, 2023). "The antipsychotic clozapine increased expression of the NRXN3 204 isoform in schizophrenia cortical neurons and rescued the spine and synapse density deficits." (PMID 37507766, 2023). "We also examined whether clozapine modulates the aberrant expression of NRXN3 isoforms in schizophrenia." (PMID 37507766, 2023). "Taken together, our findings in iPSC-derived cortical neurons recapitulate cell type-specific findings in postmortem studies in schizophrenia and have led to the identification of a specific isoform of NRXN3 that modulates synaptic deficits in schizophrenia neurons." (PMID 37507766, 2023). "By selecting SNPs associated with the schizophrenia and infant right frontal lobe white matter volume in our cohort, we identified genes overrepresented for pathways involved in neuron development, many of which have previously been validated in schizophrenia models (e.g., ZNF804A, DISC1, NRXN3)." (PMID 37037832, 2023). "Furthermore, overexpression of the NRXN3 204 isoform in schizophrenia neurons rescued the spine and synapse deficits in the cortical neurons while knockdown of NRXN3 204 in healthy neurons phenocopied spine and synapse deficits seen in schizophrenia cortical neurons." (PMID 37507766, 2023). "In cortical neurons from schizophrenia lines, exposure to 10 μM clozapine for 24 h resulted in increased expression of the NRXN3 203 and 204 isoforms, but not of the 214 and 217 isoforms." (PMID 37507766, 2023).
autism spectrum disorder (10 papers, 2017 to 2025). A spectrum of developmental disorders that includes autism, and Asperger syndrome. "The neurexins are involved in early cortical synaptogenesis, axon guidance, and intercellular communication, and mutations in NRXN3 have been identified in patients with autism spectrum disorders." (PMID 36385168, 2023). "Previous research suggested that NRXN3 variants are associated with abnormal behavioral phenotypes, such as alcohol dependence, nicotine addiction, and autism spectrum disorders." (PMID 35309141, 2022). "Importantly, Nrxn1 and Nrxn2, along with the Nrxn3, belong to the neurexin gene family, which has been linked to autism spectrum disorder (ASD), and epilepsy." (PMID 40608247, 2025). "Rare deletions in NRXN3 was linked to autism spectrum disorder." (PMID 30631343, 2018). "Interestingly, several genes (Adcyap1, Cntnap2, Grid1, Nrxn1, Nrxn3, Ucn, Tbx1, and Nr2e1), that are associated with disorders, stress response, social behaviors or autism spectrum disorders, are up-regulated specifically in the hippocampus of Del/+ mice." (PMID 28704368, 2017). "Additionally, we observed ectodermal EtOH-induced alterations in several genes, such as LHX2, SHANK2, TRIO, ZMYND8, ARX, NRXN3 and SEMA5A, that have also been associated with autism spectrum disorder (ASD) (SFARI Gene Database, 2024; accessed: 1, August, 2024)." (PMID 40401629, 2025). "The second is an intron copy number variable in the neurexin 3 (NRXN3) gene, which normally acts as a receptor and cell adhesion molecule in the nervous system, and variations in this gene are involved in autism spectrum disorder." (PMID 33918736, 2021).
Alzheimer disease (9 papers, 2010 to 2025). A progressive, neurodegenerative disease characterized by loss of function and death of nerve cells in several areas of the brain leading to loss of cognitive function such as memory and language. "According to one study, NRXN3 downregulation is the most significant risk factor for Alzheimer's disease and ageing." (PMID 37666846, 2023). "SPP1 (secreted phosphoprotein 1) and NRXN3 (neurexin 3) are already known to be associated with Alzheimer’s disease." (PMID 30220890, 2018). "In addition, when the expression of NRXN3 in an individual decreases, the risk of Alzheimer’s disease increases, but its underlying mechanism needs to be further elucidated." (PMID 35309141, 2022). "The results of functional analysis showed that NRXN3-led synaptic dysfunction plays a prominent role in the process of aging and Alzheimer’s disease-related cognitive decline." (PMID 35309141, 2022). "The meta-analysis of five GWAS identified a marker in the NRXN3 gene (rs17757879) that showed a consistent protective effect in Alzheimer’s disease." (PMID 24265751, 2013). "In subgroups of patients, CSF levels of presynaptic neurexin 3 (NRXN3), postsynaptic neurogranin (NRGN) and Alzheimer’s disease biomarkers were measured for comparison." (PMID 40840974, 2025).